CD40 (CD40 molecule)
Diseases named in the same sentence as CD40 in open-access papers (continued):
Sharing a sentence is not in itself a finding about the gene and the disease.
myeloma (22 papers, 2006 to 2024). "Up-regulating the expression of costimulatory molecules such as CD40, CD80/86, 4-1BBL, OX40L, CD70 and B7RP on the surface of myeloma cells can increase the susceptibility of myeloma cells to attack by immune effector cells." (PMID 37275861, 2023). "Engagement of CD40 enhances adhesion of myeloma cells to extracellular matrix proteins and BMSCs, and induces the production of IL-6 and VEGF by malignant cells." (PMID 29772694, 2018). "HCD122, an antibody that can disrupt CD40L-CD40 interaction but cannot activate CD40 signaling, has been used in a clinical trial to treat CD40+ multiple myeloma because of its ADCC function." (PMID 26809818, 2016). "A second anti-CD40 mAb, lucatumumab, is a fully humanized antibody demonstrated to have anti-myeloma activity both in vitro and in vivo." (PMID 27618026, 2016). "The importance of NFκB in multiple myeloma is suggested from its involvement downstream of CD40, the TNF receptor family member that is expressed in a variety of B-cell malignancies and which is associated with multiple myeloma homing." (PMID 23905066, 2012). "CD40 is expressed on the surface of myeloma cells instead of on normal mature plasma cells." (PMID 37275861, 2023). "The GSEA results showed that the altemeier response to lps with mechanical ventilation, basso CD40 signalinf up, boquest stem cell cultured vs. fresh up, boquest stem cell dn, and Boylan multiple myeloma C D dn pathways were significantly enriched in the cluster 2 subgroup." (PMID 35795203, 2022). "CD40-related uPA induced human multiple myeloma cell migration through the PI3Ksignalling pathway." (PMID 32909189, 2021). "Interestingly, CD40 simultaneously activates both the NF-κB pathways and is widely expressed on myeloma cells." (PMID 29772694, 2018). "Lucatumumab (HCD122; CHIR-12.12), a fully human anti-CD40 mAb, was shown to cause lysis of CD40+ (but not CD40-) myeloma cells via ADCC, leading to a phase I trial as monotherapy in RRMM patients (NCT00231166)." (PMID 30544512, 2018). "Consistent with this, monoclonal antibodies to CD40 block CD40L-induced NFκB activation as well as IL-6 and VEGF secretion in cultures of multiple myeloma cells and bone marrow-derived stromal cells." (PMID 23905066, 2012). "During this course, microbial Ags to promote the expression of MHC-II, CD40 and CD80 in myeloma cells may be the most critical step to stimulate tumor clonogenicity." (PMID 31870332, 2019). "Prior studies have confirmed that U266 and primary myeloma cells express B cell membrane markers, including high levels of CD86 and CD54 and detectable levels of HLA-DR, CD40 and CD80, which can be upregulated by IFN-γ combined with microbial Ags or by BCGV alone." (PMID 31870332, 2019). "Despite the role of CD40 in the pathogenesis of the disease, CD40-mediated regulation of the RelB NF-κB activity has not been investigated in the context of multiple myeloma." (PMID 29772694, 2018). "A large body of evidence indicates that the physical interaction of myeloma cells and MMSCs (cell adherence) induces the non-malignant bystander cells to secrete cyto- and chemokines, such as IL-6, CD40, TRANCE and Ras, which collectively promote myeloma proliferation and survival." (PMID 29100463, 2017). "It remains unclear if CD40-activated non-canonical signaling degrades p100 completely to promote canonical RelB:p50 activation, or crosstalk between CD40-induced NF-κB pathways contributes to aberrant RelB:p52 activation myeloma cells." (PMID 29772694, 2018). "In contrast, CD40 is highly expressed by B cell malignancies including non-Hodgkin’s lymphoma (NHL), chronic lymphocytic leukemia (CLL) and myeloma, and in that case, it promotes proliferation and inhibits the apoptosis of malignant B cells." (PMID 37215135, 2023).
ovarian carcinoma (22 papers, 2005 to 2025). A malignant neoplasm originating from the surface ovarian epithelium. "Specifically, GMPS was highly expressed in ovary cancer tissues, which was associated with RFS, whereas the expression of PR, CD40, and p21 mRNA was reduced in ovarian cancer tissues, which was associated with poor RFS." (PMID 30701134, 2019). "In contrast, the expression of PR, CD40, and p21 mRNA was reduced in ovarian cancer tissues, which was associated with poor RFS." (PMID 30701134, 2019). "Previous integrative multi-omics analyses have reported elevated CD40 levels in durable responders with ovarian cancer treated with ICI-based combination." (PMID 41182434, 2025). "High CD40 expression correlated with liver and bile duct, pancreatic, and ovarian cancers, as well as with CD28 and GITR transcripts." (PMID 41182434, 2025). "High CD40 expression was observed across multiple solid malignancies, especially liver/bile duct, pancreatic, and ovarian cancers." (PMID 41182434, 2025). "The high percentage of tumor tissue expressing CD40 in pancreatic and ovarian cancers aligns with previous research." (PMID 41182434, 2025). "CD40 expression on tumor cells was found to be common, with 80% of the NSCLC population, 40% of the ovarian cancer population, and 68% of the pancreatic adenocarcinoma population displaying some degree of CD40 expression on cancer cells." (PMID 36894898, 2023). "The correlation between CD40 expression on tumor cells and on stromal cells was particularly pronounced in ovarian cancer (R2 = 0.61), while it was less prominent in NSCLC (R2 = 0.36) and pancreatic adenocarcinoma (R2 = 0.30)." (PMID 36894898, 2023). "In this ovarian cancer cohort, 40% of the cases were positive for CD40 tumor expression according to the visual cutpoint." (PMID 36894898, 2023). "Among TAM repolarisation strategies, mAbs targeting the TAM co-stimulatory molecule CD40 has been the focus of clinical investigation in ovarian cancer." (PMID 35020853, 2022). "Clinically, a Phase I trial using anti-CD40 IgG2 mAb CDX-1140 with anti-PD-1 IgG4 mAb Pembrolizumab (Keytruda) is currently recruiting ovarian cancer patients (NCT03329950)." (PMID 35020853, 2022). "Pre-clinically, anti-CD40 mAbs have predominantly been investigated in other malignant diseases; however, in an ovarian cancer xenograft mouse model, a recombinant CD40L inhibited tumour growth." (PMID 35020853, 2022). "In our current study, we found elevated CD40 expression in MOSE-II cells compared with MOSE-I cells; however, CD40 expression was reduced in ovarian cancer tissues, which is opposite the findings of a previous study." (PMID 30701134, 2019). "The bioinformatic data revealed four genes (i.e., guanosine 5′-monophosphate synthase (GMPS), progesterone receptor (PR), CD40, and p21 (cyclin-dependent kinase inhibitor 1A)) to play an important role in ovarian cancer progression." (PMID 30701134, 2019). "Similar effects of CD40 ligation on FasL expression have been noted in mouse Langerhan’s cells, human hepatocytes and ovarian cancer cells." (PMID 23940537, 2013). "Furthermore, in a trial for recurrent ovarian cancer, a high CD40 gene signature was a key feature in patients achieving durable clinical benefit from immunotherapy, linking high CD40 expression to an immunologically “hot” state permissive for response." (PMID 41182434, 2025). "Following this multi-tumor screening, the large NSCLC, ovarian cancer, and pancreatic adenocarcinoma cohorts were used to further explore patterns of CD40 expression, as well as potential prognostic value and possible correlations with clinicopathologic features." (PMID 36894898, 2023). "Similar to the NSCLC results, CD40 expression in ovarian cancer showed considerable intratumoral heterogeneity (R2 = 0.37), high concordance between serial sections (R2 = 0.79), and some correlation between expression in the tumor and stroma compartments (R2 = 0.61)." (PMID 36894898, 2023).
ovarian carcinoma (continued). "CD40 expression on tumor cells was then similarly assessed in the ovarian cancer cohort (YTMA 264)." (PMID 36894898, 2023). "While in some tumors, CD40 agonists may singlehandedly activate DCs, in other tumors, like ovarian carcinoma, combining CD40 agonists with TLR activation will be necessary to revert DCs from immune-suppressors into functional APCs." (PMID 24339824, 2013). "In this review we pointed out that ovarian cancer tumor cells may (over)express immunoregulatory molecules such as ligand "Letal", CD40 and Stat-3 which stimulate immune response." (PMID 16164749, 2005). "Interestingly, CD40-L has been shown to sensitize epithelial ovarian cancer cells to cisplatin treatment, clearly indicating that activation of the CD40 intracellular pathway in cancer cells can be of relevance beyond CD40 effect in establishing the adaptive immune response." (PMID 37373140, 2023). "Nonetheless, there are ongoing clinical trials investigating the use of vanucizumab in combination with atezolizumab (anti‐PD‐L1) or CD40 agonists, although atezolizumab plus vanucizumab has thus far not shown significant benefit over the monotherapies in platinum‐resistant recurrent ovarian cancer." (PMID 34125494, 2021). "CD40 distribution and patterns of expression were further explored in larger cohorts of non-small cell lung cancer (NSCLC), ovarian cancer, and pancreatic adenocarcinoma, and correlated with clinicopathologic characteristics and outcome." (PMID 36894898, 2023). "The large cohort, population-based assessments demonstrated the variability of CD40 expression by tumor cells within NSCLC (80%), ovarian cancer (40%), and pancreatic adenocarcinoma (68%)." (PMID 36894898, 2023). "In conclusion, this study demonstrates the quantitative, protein-based assessment of CD40 expression by tumor cells, with a particular focus on NSCLC, ovarian cancer, and pancreatic adenocarcinoma." (PMID 36894898, 2023). "CD40 and CD70 are detected on a wide range of cancer cells (including ovarian cancer cells) and cells from their microenvironment." (PMID 33287223, 2020). "In conclusion, this study profiled differentially expressed genes using the ovarian cancer progression model and identified four (i.e., GMPS, PR, CD40, and p21) as prognostic markers for ovarian cancer patients." (PMID 30701134, 2019). "It has been reported that in situ stimulation of CD-40 and TLR-3 transforms ovarian cancer-infiltrating DCs from immunosuppressive to immunostimulatory cells." (PMID 24475147, 2014). "Metastasis in the lymph nodes of mice bearing ovarian cancer cells was apparent in H&E staining of lymph node tissue sections, as well as immunostaining for CA125 or CD40." (PMID 24502459, 2014). "For example, CD40 expression on tumor cells was shown to have a negative prognostic effect in NSCLC, while CD40 expression has also been cited as having an anti-tumor effect in several other cancer types, including ovarian cancer." (PMID 36894898, 2023). "After rigorous validation of an antibody for CD40, quantitative immunofluorescence was employed to screen for CD40 expression on tumor cells across nine cancer types, and to complete large cohort, population-based assessments in NSCLC, ovarian cancer, and pancreatic adenocarcinoma." (PMID 36894898, 2023). "CD40 was highly expressed in ovarian cancer cell lines and tumor samples but not in normal ovarian tissue." (PMID 30701134, 2019). "However, a Phase I/II trial of ABBV-428, a bispecific mAb targeting CD40 (as an agonist) and tumour cell marker mesothelin, was not able to replicate these promising anti-tumoural effects in ovarian cancer patients." (PMID 35020853, 2022). "Secondly, evidence has emerged that TAM-mediated immunosuppression underpins the lack of efficacy displayed by ovarian cancer patients in response to ICB, and therefore ICB in combination with anti-CD40 treatment has been advanced as a potentially efficacious strategy." (PMID 35020853, 2022).
Alzheimer disease (21 papers, 2005 to 2026). A progressive, neurodegenerative disease characterized by loss of function and death of nerve cells in several areas of the brain leading to loss of cognitive function such as memory and language. "With the elevation of CD48 and CD40 genes in Alzheimer's disease, associations of protein levels were also markedly increased in tissues." (PMID 36520044, 2023). "Increased expression of CD40 is associated with microglial activation, which has been found to contribute to cognitive impairments and the pathogenesis of Alzheimer’s disease." (PMID 36873953, 2023). "In addition, depression-like behavior was associated with abnormal microglial expression of CD40 in a rat model of Alzheimer’s disease." (PMID 38297317, 2024). "A study on Alzheimer’s disease (AD) showed that apigenin and luteolin can decrease CD40 expression on the surface of microglial cells by investigating the upstream signal transducer and activator of transcription (STAT1) signaling pathway." (PMID 41515450, 2026). "CD40 is important in neuroinflammation and is a potential biomarker for Alzheimer’s disease." (PMID 39606031, 2024). "Indeed, the upregulation of both CD48 and CD40 genes was significantly increased in the severe Alzheimer's disease group." (PMID 36520044, 2023). "We observed a marked elevation of CD48 and CD40 genes in Alzheimer's disease." (PMID 36520044, 2023). "CD40 is a major regulator of dendrite growth and elaboration in the developing brain and contributes to synaptic degeneration in Alzheimer’s disease (AD), which may have developmental origins." (PMID 36791193, 2023). "In addition, in the early stage of Alzheimer’s disease, CD40 has been reported to play a unique role in the amyloid β-protein (Aβ)-induced microglial activation." (PMID 33479212, 2021). "CD40 expression in endothelial cells has been implicated in several pathologic conditions of the CNS including Alzheimer’s disease and human immunodeficiency virus 1 (HIV-1) encephalitis, where an important role of CD40 has been demonstrated in BBB disruption." (PMID 32867217, 2020). "For example, several TNF receptor superfamily (TNFRSF)/ligands such as CD40/CD40L and TWEAK/FN14 also participate in glial cell‐mediated central/neuronal inflammatory diseases such as Alzheimer's disease and MS 31, 32 and are considered as a potential therapeutic target." (PMID 29744298, 2018). "Although these data suggest a potential role for CD40L in Alzheimer's disease pathology in transgenic mice they do not cast light on whether this effect is due to inhibition of signaling via CD40 or whether it is due to the mitigation of some other unknown role of CD40L." (PMID 16504112, 2006).
Immunodeficiency (20 papers, 2011 to 2025). Failure of the immune system to protect the body adequately from infection, due to the absence or insufficiency of some component process or substance. "Mutation of the CD40 gene can result in type 3 hyper‐IgM immunodeficiency, characterized by an inability to undergo isotype switching, an inability to mount an antibody‐specific immune response, and a lack of germinal centre formation." (PMID 35092700, 2022). "Decreased expression of CD40 on monocytes of children with IgAD has previously been observed and CD40 has also been implicated in the etiology of a variety of immune diseases such as RA, asthma, T1D and MS." (PMID 34976003, 2021). "Polymorphisms of the cluster of differentiation 40 (CD40) gene have recently been identified to be associated with the risk to several immune diseases." (PMID 21976957, 2011). "For example, the bone-marrow disease hyper-IgM immunodeficiency could arise from mutations in CD40 gene, affecting B cells, or mutations in CD40 ligand (CD40LG), affecting CD4 T cells." (PMID 38197427, 2024). "Interestingly, the reduced incidence of Tfh cells in patients with immune deficiencies caused by mutations in CD40 ligand has raised questions about a potential role of CD40 in both the generation and maintenance of Tfh cells." (PMID 36254574, 2022). "Low or absent CD40 expression may result in impaired antibody production and has been linked to immunodeficiencies characterized by defective Ig production." (PMID 28680905, 2017). "As expected, hyper-IgM immunodeficiency was found to likely affect naïve B cells through CD40 (receptor; PrEDiCT = 2.9, FDR = 0.06), and CD4αβ T cells through CD40LG (ligand; PrEDiCT = 3.7, FDR <0.001)." (PMID 38197427, 2024). "CD40 is involved in transducing activating signals for inflammation and immune disorders, and CD40 is often expressed on dendritic cells, B cells, and macrophages." (PMID 38530810, 2024). "CD40 is therefore a pleiotropic locus for both psychiatric disorders and immune diseases, which supports the notion of a mechanistic link between the immune system and the neural system." (PMID 33479212, 2021). "The inability of mutated CD40L protein to bind to CD40 affects CD4 T-cell and B-cell interactions, impairing CSR, SHM, T-cell co-stimulation, and development of memory B cells, resulting in a combined immunodeficiency." (PMID 30319630, 2018). "Patients with CSR/HIGM syndromes that are combined immunodeficiencies (e.g., X-HIGM, CD40 deficiency, NEMO, and NFKBIA) also require PJP prophylaxis with trimethoprim-sulfamethoxazole or pentamidine." (PMID 30319630, 2018). "Several studies have shown that animal models of rheumatoid arthritis, experimental autoimmune encephalitis, and lupus nephritis yielded first remarks for the importance of CD40/CD40L pathways in immune diseases." (PMID 26528290, 2015). "The implication of CD40/CD40L axis in immune system disorders due to its important role as signal transduction pathway among immune cells is well documented." (PMID 26528290, 2015). "Loss-of-function mutations in both CD40 and CD40L result in immunodeficiency, but only in the homozygous state, indicating that 50% inhibition of CD40-CD40L signaling (as observed in heterozygous mutation carriers) should be safely tolerated in humans." (PMID 23696745, 2013). "Additionally, CD40-targeting drugs have therapeutic roles in both cancer and immune diseases, depending on their specific pharmacological actions." (PMID 40868097, 2025). "For example, CD28, CD40, and TNFRSF4 (OX40) antagonists are in early stage clinical trials for treatment of various immune disorders, whereas CD28, CD40, and TNFRSF4 (OX40) agonists are in early stage clinical trials for various cancer indications." (PMID 28822103, 2018).